FBXO45 (F-box protein 45)
Description:
Component of E3 ubiquitin ligase complex consisting of FBXO45, MYCBP2 and SKP1. Functions in substrate recognition but also plays an important role in assembly of the complex. Required for normal neuromuscular synaptogenesis, axon pathfinding and neuronal migration (By similarity). Regulates neuron migration during brain development through interaction with N-cadherin/CDH2 after secretion via a non-classical mechanism (By similarity). Plays a role in the regulation of neurotransmission at mature neurons (By similarity). May control synaptic activity by controlling UNC13A via ubiquitin dependent pathway (By similarity). Specifically recognizes TP73, promoting its ubiquitination and degradation. Polyubiquitinates NMNAT2, an adenylyltransferase that acts as an axon maintenance factor, and regulates its stability and degradation by the proteasome. Also acts by ubiquitinating FBXW7 during prolonged mitotic arrest and promotes FBXW7 proteasomal degradation. Induces subsequently an increase in mitotic slippage and prevents mitotic cell death. In response to influenza infection, mediates interferon-lambda receptor IFNLR1 polyubiquitination and degradation through the ubiquitin-proteasome system by docking with its intracellular receptor domain.
Synonyms: FBX45
Tractability: Antibody: UniProt places it where antibodies can reach, with high confidence; its Gene Ontology location is reachable by antibodies, with high confidence. PROTAC: ubiquitination databases record sites on it; its protein half-life has been measured.
Gene: Protein-coding gene on chromosome 3 (196,568,611 to 196,589,059, forward strand). Ensembl gene ENSG00000174013.
Subcellular location: Secreted; Postsynaptic cell membrane; Presynaptic cell membrane; Nucleus
Subcellular location (Human Protein Atlas): Cytosol; Nucleoplasm; Plasma membrane; Vesicles; Predicted to be secreted
Gene Ontology:
Molecular function: protein binding; ubiquitin-like ligase-substrate adaptor activity
Biological process: DNA damage response; protein K48-linked ubiquitination; protein ubiquitination; ubiquitin-dependent protein catabolic process; proteasome-mediated ubiquitin-dependent protein catabolic process; synapse assembly involved in innervation; synaptic assembly at neuromuscular junction; regulation of synaptic vesicle exocytosis
Cellular component: extracellular region; nucleoplasm; nucleus; cytoplasm; postsynaptic membrane; presynaptic membrane; SCF ubiquitin ligase complex; synapse; ubiquitin ligase complex; glutamatergic synapse; organelle; postsynaptic cytosol; postsynaptic density; presynapse; presynaptic cytosol
Genetic constraint (gnomAD): Loss-of-function variants: 3 observed, 19.62 expected, observed/expected ratio (o/e) 0.15, 90% interval 0.069 to 0.4. The upper end of that interval is the gene's LOEUF score, 0.4, which puts it in group 1 of 6, group 1 being the genes least tolerant of losing a copy. Missense variants: 216 observed, 338.26 expected, observed/expected ratio (o/e) 0.64, 90% interval 0.57 to 0.71. Synonymous variants: 154 observed, 131.63 expected, observed/expected ratio (o/e) 1.17, 90% interval 1.02 to 1.34.
Homologues: Orthologues: chimpanzee FBXO45 (100% identical), macaque FBXO45 (100% identical), rabbit FBXO45 (99% identical), guinea pig FBXO45 (96% identical), dog FBXO45 (95% identical), mouse Fbxo45 (95% identical), rat Fbxo45 (95% identical), pig FBXO45 (92% identical), tropical clawed frog fbxo45 (85% identical), zebrafish fbxo45 (80% identical), Drosophila melanogaster Fsn (62% identical), Caenorhabditis elegans fsn-1 (52% identical). Paralogues in human: SPSB4 (33% identical), SPSB2 (30% identical), SPSB1 (29% identical), SPSB3 (21% identical).
Diseases named in the same sentence as FBXO45 in open-access papers:
FBXO45 is named in the same sentence as 37 diseases in open-access papers, as found by Europe PMC text mining. Sharing a sentence is not in itself a finding about the gene and the disease. The quoted sentences say what the papers report.
breast carcinoma (10 papers, 2020 to 2024). "In this study, we used numerous approaches to determine the functions of FBXO45 and its underlaying mechanisms in breast cancer pathogenesis." (PMID 38773471, 2024). "FBXO45 has been described as a tumor promoter or linked to the pathogenesis of pancreatic, esophageal, liver, gastric, lung, and breast carcinomas." (PMID 36379255, 2022). "It is necessary to determine whether FBXO45 expression is negatively associated with Bim expression in breast cancer tissues." (PMID 38773471, 2024). "Strikingly, FBXO45 expression was associated with poor survival of breast cancer patients." (PMID 38773471, 2024). "In conclusion, FBXO45 performs oncogenic role in breast cancer via targeting the ubiquitination and degradation of Bim." (PMID 38773471, 2024). "Understanding the regulatory mechanisms of FBXO45 in breast tumorigenesis is important for potential therapeutic interventions in breast cancer." (PMID 38773471, 2024). "Together, inhibition of FBXO45 reduced cell proliferation and invasion and induced apoptosis in breast cancer." (PMID 38773471, 2024). "Exploration of the regulatory mechanisms of FBXO45 in breast cancer development is pivotal for potential therapeutic interventions in patients with breast cancer." (PMID 38773471, 2024). "We found that overexpression of FBXO45 in MDA MB-231 cells facilitated tumor growth in breast cancer xenograft mouse model and breast orthotopic tumor model." (PMID 38773471, 2024). "We found that downregulation of FBXO45 inhibited cell proliferation, while upregulation of FBXO45 elevated cell proliferation in breast cancer." (PMID 38773471, 2024). "Using GEPIA database, we found that FBXO45 was highly expressed in breast cancer patients compared with normal control." (PMID 38773471, 2024). "Taken together, FBXO45 upregulation promoted cell proliferation and attenuated cell apoptosis in breast cancer." (PMID 38773471, 2024). "Silencing of FBXO45 induced cell apoptosis, whereas overexpression of FBXO45 inhibited cell apoptosis in breast cancer." (PMID 38773471, 2024). "By a systematic analysis, FBXO45 was uncovered to be a potential target and prognostic biomarker for breast cancer." (PMID 38773471, 2024). "There is literature proving that Fbxo45 is also associated with the poor prognosis of gastric cancer and degradation of EMT‐related transcriptional factors in breast cancer or prostate cancer." (PMID 35838331, 2022). "Mounting evidences have revealed the role of F-box proteins in regulating EMT in multiple types of tumors, including FBXW7 in lung cancer and gastric cancer, FBXO11 in breast cancer and gastric cancer, and FBXO45 in prostate cancer and PCa." (PMID 34249081, 2021). "In agreement with previous studies, we showed that FBXO45 functions as a tumor suppressor, particularly for more aggressive breast cancer subtypes, indicating that the anti-metastatic effects of FBXO45 are strikingly cancer-type specific." (PMID 33966034, 2021). "Altogether, these results demonstrate that DNAJB9 governs FBXO45 expression through their interaction in breast cancer." (PMID 33966034, 2021). "We further determined whether downregulation of FBXO45 inhibited proliferation of breast cancer cells via regulation of BIM pathway." (PMID 38773471, 2024). "To explore whether FBXO45 expression is correlated with survival of breast cancer patients, we used bioinformatics to analyze the expression of FBXO45 in breast cancer patients." (PMID 38773471, 2024). "Our study could provide the rational for targeting FBXO45 to obtain benefit for breast cancer patients." (PMID 38773471, 2024). "Inhibition of FBXO45 reduced proliferation of breast cancer cells and increased cell apoptosis." (PMID 38773471, 2024).
breast carcinoma (continued). "Moreover, we used FBXO45 shRNA transfection and observed that depletion of FBXO45 reduced cell proliferation and colony formation in breast cancer cells." (PMID 38773471, 2024). "Moreover, the survival periods of breast cancer patients with high expression of FBXO45 were shorter compared with these patients with low expression of FBXO45." (PMID 38773471, 2024). "Altogether, FBXO45 expression is correlated with poor survival in breast cancer patients." (PMID 38773471, 2024). "In addition, FBXO45 cDNA transfection inhibited cell apoptosis in breast cancer cells after FBXO45 cDNA transfection." (PMID 38773471, 2024). "Altogether, modulating FBXO45/Bim axis could be a promising strategy for breast cancer therapy." (PMID 38773471, 2024). "Altogether, targeting FBXO45/Bim axis could be a promising strategy for breast cancer treatment." (PMID 38773471, 2024). "Furthermore, FBXO45 shRNA led to invasion inhibition of breast cancer cells." (PMID 38773471, 2024). "Altogether, FBXO45 promoted the ubiquitination and degradation of BIM in breast cancer." (PMID 38773471, 2024). "Furthermore, data from LinkedOmics showed that the protein expression of FBXO45 was positively correlated (R = 0.129; p < 0.0001) with DNAJB9 protein expression in 102 breast cancer tissue samples." (PMID 33966034, 2021). "Because DNAJB9 modulated the FBXO45-mediated negative regulation of ZEB1, we further investigated whether DNAJB9 and FBXO45 affect the metastasis of breast cancer." (PMID 33966034, 2021). "Mechanistically, DNAJB9 can interact with FBXO45 (F-box/SPRY domain-containing protein 1) ubiquitin ligase to promote FBXO45 protein stability, which reduces the abundance of ZEB1 by proteasomal degradation, leading to repressed EMT, invasion, and metastasis of breast cancer cells." (PMID 36499297, 2022). "Importantly, given that DNAJB9 and FBXO45 are tightly correlated in patients with breast cancer, our findings highlight DNAJB9 as a potential biomarker for predicting patient survival and a novel therapeutic target for treating patients with breast cancer." (PMID 33966034, 2021). "Similarly, FBXO45 cDNA transfection reduced the expression of BIM protein in MCF-7 and MDA MB-231 cells, while FBXO45 cDNA transfection did not change the BIM mRNA levels in breast cancer cells." (PMID 38773471, 2024).
gastric cancer (5 papers, 2020 to 2023). A primary or metastatic malignant neoplasm involving the stomach. "It was shown that FBXO45 is highly expressed in gastric cancer and squamous-cell lung carcinoma and correlated with shortened survival." (PMID 36980776, 2023). "However, gastric cancer patients with low FBXO45 expression exhibited poorer outcomes, such as worse survival, than those with high FBXO45 expression." (PMID 32655893, 2020).
colorectal cancer (4 papers, 2021 to 2024). A primary or metastatic malignant neoplasm that affects the colon or rectum. "Recent studies have reported that FBXO45 may play key roles in the tumorigenesis and prognosis of squamous cell lung carcinoma and colorectal cancer." (PMID 34779401, 2021).
lung carcinoma (4 papers, 2021 to 2023). "Fbxo45 activates ERK activity in lung cancer through NP-STEP46 degradation mediated by K6 linkage to ubiquitin chains." (PMID 37828084, 2023). "Likewise, a tissue microarray chip including 71 pairs of LUAD and adjacent tissues was examined by immunohistochemistry, which indicated that Fbxo45 protein expression is markedly increased in lung cancer tissues compared with the normal adjacent lung tissues." (PMID 35838331, 2022). "To determine Fbxo45 mRNA expression in lung cancer, we used the ONCOMINE database to reveal that the relative mRNA levels of Fbxo45 were significantly higher in various types of human lung cancer than those in normal lung tissues." (PMID 35838331, 2022). "Intriguingly, Fbxo45 was specifically and strongly expressed in tumor cells of NSCLC according to the indirect immunofluorescence analysis in paraffin‐embedded human lung carcinoma, including LUAD with TTF1‐positive and LUSC with TTF1‐negative." (PMID 35838331, 2022). "Similarly, Fbxo45 silencing led to EMT and enhanced cell migration capacity in lung cancer cells." (PMID 35279684, 2022). "In addition, the other effect molecules closely associated with the ERK1/2 signal, including the phosphatase Shp2, which is supposed to be a prospective target for lung cancer therapy, showed no significant change upon the Fbxo45 expression." (PMID 35838331, 2022).
pancreatic cancer (4 papers, 2020 to 2024). "Notably, Fbxo45 expression was negatively associated with USP49 expression in pancreatic cancer tissues." (PMID 35279684, 2022). "Fbxo45 serves as an oncoprotein to facilitate pancreatic oncogenesis by regulating the stability of the tumor suppressor USP49 in pancreatic cancer." (PMID 35279684, 2022). "We conducted several approaches, including transfection, coIP, real-time polymerase chain reaction (RT-PCR), Western blotting, ubiquitin assays, and animal studies, to explore the role of Fbxo45 in pancreatic cancer." (PMID 35279684, 2022). "Consistently, our study also showed that Fbxo45 can regulate the expression of Zeb1 and N-cadherin in pancreatic cancer cells." (PMID 35279684, 2022). "FBXO45 is highly expressed in several human cancers, such as squamous cell lung carcinoma and pancreatic cancer, and correlated with shortened OS and poorer outcomes." (PMID 33966034, 2021). "We observed the basal expression levels of Fbxo45 and USP49 in several pancreatic cancer cell lines." (PMID 35279684, 2022). "Functionally, Fbxo45 increases cell viability and motility capacity by targeting USP49 in pancreatic cancer cells." (PMID 35279684, 2022). "Furthermore, we used bioinformatics to analyze the expression of Fbxo45 and USP49 in human pancreatic tumor samples." (PMID 35279684, 2022).
prostate carcinoma (4 papers, 2021 to 2024). A carcinoma that arises from epithelial cells of the prostate gland. "FBXO45 was identified as a prognostic biomarker in TMPRSS2-ERG-positive prostate cancer." (PMID 38773471, 2024). "While FBXO45 has been suggested to have prognostic potential in various cancers, its specific role in prostate carcinoma (PCA) remains unclear." (PMID 36980776, 2023).
squamous cell lung carcinoma (4 papers, 2021 to 2024). A carcinoma arising from squamous bronchial epithelial cells. "FBXO45 was found to be a target of miR-30a-5p in lung squamous cell carcinoma and regulated cell proliferation." (PMID 38773471, 2024).
autism (3 papers, 2013 to 2016). Persistent deficits in social interaction and communication and interaction as well as a markedly restricted repertoire of activity and interest as well as repetitive patterns of behavior. "Fbxo45 is one of several genes deleted in 3q29 microdeletion syndrome, which results in autism, intellectual disability, and schizophrenia." (PMID 27008623, 2016). "Interestingly, microdeletions and microduplications that include Dlk/MAP3K12, a likely Fbxo45 ubiquitination target, also result in intellectual disability and autism." (PMID 27008623, 2016). "Since mounting evidence has established autism as a disorder of the synapses, we tested whether rare genetic variants in TSC1, TSC2, MYCBP2, RHEB and FBXO45, genes that regulate mTORC1 signaling and/or play a role in synapse development and function, contribute to the pathogenesis of idiopathic ASD." (PMID 23514105, 2013). "Several molecules in PHR protein signaling pathways also are associated with schizophrenia and autism, including the Tuberous Sclerosis Complex, FSN-1/Fbxo45, and ESS-2/DGCR14." (PMID 26464359, 2015).
colon cancer (2 papers, 2019 to 2022). "Normalization to Fbxo45, but not Siah1, further significantly reduced the OS of colon cancer patients." (PMID 30979372, 2019). "When Zeb1 expression was normalized to that of Fbxo45, but not Siah1, the DFS of colon cancer patients with higher Zeb1/Siah1 levels was statistically significantly reduced compared to patients with lower values." (PMID 30979372, 2019).
glioma (2 papers, 2024). A benign or malignant brain and spinal cord tumor that arises from glial cells (astrocytes, oligodendrocytes, ependymal cells). "Another study found that a partial reverse complementary lncRNA called CACNA1C-AS2 inhibits the growth of glioma cells by negatively regulating the expression of Fbxo45 in glioma through rescue experiments." (PMID 38967893, 2024).
hepatocellular carcinoma (2 papers, 2023). A malignant tumor that arises from hepatocytes. "In addition, F-box/SPRY domain-containing protein 1 (FBXO45), an E3-ubiquitin ligase, was found to promote IGF2BP1 ubiquitination and attenuate hepatocellular carcinoma (HCC) progression." (PMID 36632454, 2023).
influenza infection (2 papers, 2022 to 2025). "In this study, we have observed that influenza infection triggers IFNLR1 degradation mediated by FBXO45 that targets IFNLR1 for ubiquitination and degradation in epithelia to impair IFN-λ signaling." (PMID 36379255, 2022). "We demonstrate that FBXO45, induced in response to influenza infection, mediates IFNLR1 protein polyubiquitination and degradation through the ubiquitin-proteasome system by docking with its intracellular receptor domain." (PMID 36379255, 2022). "Together, these data suggest that FBXO45 plays a key role in attenuating antiviral host defense to facilitate influenza virulence." (PMID 36379255, 2022). "FBXO45 was recently shown to be involved in influenza infection by promoting IFNLR1 ubiquitination and degradation, suggesting that FBXO45 may exert potential regulatory functions in virus-host interactions." (PMID 39936917, 2025).
abortion (1 paper, 2022). the ending of pregnancy by removing a fetus or embryo before it can survive outside the uterus. "Furtherly, 3xFlag tagged Fbxo45 was re‐introduced into the KO‐cells using the lentiviral system and reactivated the suppressed pERK due to Fbxo45‐abortion." (PMID 35838331, 2022).
esophageal cancer (1 paper, 2024). A primary or metastatic malignant neoplasm involving the esophagus. "Moreover, bioinformatics analysis showed that FBXO45 could be a potential oncogene in esophageal cancer." (PMID 38773471, 2024).
esophageal squamous cell carcinoma (1 paper, 2024). Esophageal squamous cell carcinoma (ESCC) is a type of esophageal carcinoma (EC) that can affect any part of the esophagus, but is usually located in the upper or middle third. "Wang and colleagues reported that FBXO45 accelerated tumor malignant progression via regulation of ubiquitination and degradation of GGNBP2 in esophageal squamous cell carcinoma." (PMID 38773471, 2024).
Intellectual disability (1 paper, 2016). "Fbxo45 is duplicated in patients with 3q29 microduplication syndrome, which results in intellectual disability and seizures." (PMID 27008623, 2016).
mesothelioma (1 paper, 2022). A usually malignant and aggressive neoplasm of the mesothelium which is often associated with exposure to asbestos. "The forest plot for overall survival (OS) in Pan‐cancer also showed that Fbxo45 expression is significantly related to the hazard ratio in NSCLC, as well as brain low‐grade glioma (LGG), liver hepatocellular carcinoma (LIHC), and mesothelioma (MESO)." (PMID 35838331, 2022).
metastatic disease (1 paper, 2023). "In this study, we investigated the prognostic role of FBXO45 in PCA and its functional role in metastatic disease progression." (PMID 36980776, 2023).